Y_RNA (Y RNA )
Gene: Miscellaneous RNA gene on chromosome 10 (73,346,936 to 73,347,048, forward strand). Ensembl gene ENSG00000207473.
Homologues: Orthologues: chimpanzee Y_RNA (100% identical), macaque Y_RNA (81% identical). Paralogues in human: Y_RNA (89% identical), Y_RNA (88% identical), RNY1 (88% identical), RNY1P8 (88% identical), Y_RNA (87% identical), Y_RNA (86% identical), RNY1P11 (85% identical), Y_RNA (85% identical), Y_RNA (84% identical), Y_RNA (83% identical), Y_RNA (82% identical), RNY1P10 (81% identical), and 97 more.